LINC00926 (long independently transcribed non-coding RNA 926)
Gene: Long non-coding RNA gene on chromosome 15 (57,300,317 to 57,307,769, forward strand). Ensembl gene ENSG00000247982.
Diseases named in the same sentence as LINC00926 in open-access papers:
LINC00926 is named in the same sentence as 4 diseases in open-access papers, as found by Europe PMC text mining. Sharing a sentence is not in itself a finding about the gene and the disease. The quoted sentences say what the papers report.
breast carcinoma (3 papers, 2022 to 2023). "In breast cancer, the level of LINC00926 is regulated by the transcription factor FOXO3A, which is able to exert potent tumor suppressive effects." (PMID 37204526, 2023). "The FOXO3A/LINC00926/PGK1 axis effectively inhibits the Warburg effect in breast cancer and is a potential therapeutic target for breast cancer." (PMID 37204526, 2023). "In breast cancer patients, the FOXO3A/LINC00926/PGK1 axis regulates breast cancer glycolysis, tumour growth, and lung metastasis both in vitro and in vivo." (PMID 37723547, 2023). "Zhong chu demonstrated that LINC00926 interacts with PGK1 and promotes its ubiquitination and degradation by binding to the E3 ligase STUB1, which is the first E3 ligase responsible for PGK1 degradation and may be a potential therapeutic target for breast cancer." (PMID 37723547, 2023).
latent infections (1 paper, 2023). "Furthermore, we found that lnc-XPNPEP1-5, lnc-CASKIN2-2, lnc-HSPA13-6, lnc-CLIC5-1, and LINC02502 were significantly downregulated in TB-infected patients, while LINC00528, lnc-SLC45A4-3, and LINC00926 were significantly upregulated in TB patients and latent infections." (PMID 38156018, 2023).
cancer (1 paper, 2021). A tumor composed of atypical neoplastic, often pleomorphic cells that invade other tissues. "Abnormal expression of LINC00926 has been observed in several cancers." (PMID 34290738, 2021).
LINC00926 also shares sentences with these, for which no sentence is quoted: acute myeloid leukemia (1 paper).